S100A8 (S100 calcium binding protein A8)
Diseases named in the same sentence as S100A8 in open-access papers (continued):
Sharing a sentence is not in itself a finding about the gene and the disease.
tumor (continued). "Tumor cells express scavenger receptor genes, but not AGER and TLR4 at significant levels, suggesting that these cells are primarily targeted by S100A8/A9 heterodimers." (PMID 27215396, 2016). "Although the apoptosis increased in EACC, S100A8 and S100A9 might still play a more prominent role in cell proliferation and pro-tumor function, which can explain its negative correlation with apoptosis." (PMID 39575241, 2024). "Notably, S100A8 and S100A9 were not confined to increased expression solely in mesenchymal immune cells; their expression was also notably elevated within tumor cells, exceeding levels found in normal tissues." (PMID 38817853, 2024). "Notably, under neoplastic conditions, S100A8 and S100A9 are not solely derived from mesenchymal cells but are also highly expressed in tumor epithelial cells." (PMID 38817853, 2024). "Importantly, in the supernatant of SCC VII and 4T1 tumor cells, we only detected large amounts of uric acid, whereas HMGB1 levels were low and S100A8/9 was not present (not shown)." (PMID 34876407, 2021). "The analysis of TCGA transcript levels of high abundant proteins found in our study revealed that a good fraction of them, including S100A8 and S100A9, showed higher transcripts in GBM and significant positive correlation with stromal scores and negative correlation with tumor purity score." (PMID 30808902, 2019). "Interestingly, S100A8 and S100A9 dysregulation was similar across all tumor grades (T) and was independent of nodal involvement (N) or distant metastasis (M)." (PMID 26883112, 2016). "All together, these findings pointed out that S100A9, rather than S100A8/S100A9, could be the main mediator of inflammatory diseases and tumours and, more importantly, is emerging as a potential target for the treatment of malignant diseases." (PMID 23626736, 2013). "Thus, its interesting to note that several genes thought to play a role in the processes of invasion, tumour progression and metastasis (MME, STAT3, DCBLD2, S100A10, CD9, S100A8) were highly downregulated in the NE vs the non-NE tumour group." (PMID 18827820, 2008). "Unlike S100A8/A9, the abundance of CXCL1, CXCL2, and CXCL5 chemokines in scaffolds neither increased following the infiltration of cancer-induced neutrophils in MNs after tumor inoculation nor decreased after systemic depletion of neutrophils in tumor-bearing mice." (PMID 37553342, 2023). "However, in vitro stimulation of human-derived macrophages with S100A8/S100A9 purified proteins failed to induce cytokine production, possibly due to required interaction of the S100A8/S100A9 heterodimer with additional factors from the tumor microenvironment." (PMID 35440136, 2022). "Interestingly, DAMP molecules High-Mobility Group Protein B1 and S100A8/9 have the ability to bind heparin sulfate and heparin sulfate proteoglycans, which are known to be coligands involved in NCR dependent recognition of tumor cells, resulting in secretion of IFN-γ but not cytotoxicity." (PMID 23527218, 2013).
cancer (471 papers, 2005 to 2026). A tumor composed of atypical neoplastic, often pleomorphic cells that invade other tissues. "As previously reported, overexpression of S100A8 is associated with tumorigenesis and poor prognosis in various cancers." (PMID 38361783, 2024). "PAWR, implicated in various cancers, and S100A8, a regulator of inflammatory responses, further expanded the repertoire of potential therapeutic targets." (PMID 38384278, 2024). "Other studies stated that downregulation of S100A8/A9 correlated strongly with a loss of cell cycle control and increased growth of carcinoma cells, which is of special interest since OLP is considered an oral potentially malignant lesion." (PMID 38750317, 2024). "Those genes contributing to ‘defense response’ and ‘peptidase activity’ terms in recurrent tissues were mainly composed of a number of genes previously associated with cancer such as S100A8, S100A9, TANK, or ADORA2B." (PMID 37177979, 2023). "Both increased S100A8 CN and protein expression in cancer cells were associated with high Ki67 status, high mitotic count and high histopathological grade." (PMID 37450087, 2023). "Among the veritable mountain of molecules associated with cancer metastasis, S100A8/A9, a heterodimer complex of S100A8 and S100A9 proteins, is especially noteworthy." (PMID 36142212, 2022). "When assessing fatal events at 1‐year follow‐up, IFi (HR 1.11; 95% CI = 1.01–1.22; p = 0.024) and S100A8/A9 (HR 2.28; 95% CI = 1.20–4.31; p = 0.012) predicted all‐cause mortality independently of confounders (age and cancer)." (PMID 35166014, 2022). "To explore the underlying processes by which S100A8 contributes to cancer carcinogenesis, we constructed an S100A8 PPI network." (PMID 35646116, 2022). "Further, high S100A8 expression is associated with increased cancer relapse and lower overall and disease-free survival." (PMID 35633393, 2022). "S100A8 expression is associated with cancer stage in various malignancies, including CESC, ESCA, HNSC, KIRC, and LGG." (PMID 35646116, 2022). "Among the genes with a high correlation with S100-eRNA, our attention was focused on S100A8/A9, a heterodimer that is overexpressed in many cancers and associated with suppressive TME." (PMID 35586193, 2022). "S100A8/A9 expression in cancer cells causes enhanced immune cell infiltration, especially by neutrophils." (PMID 33567747, 2021). "For secreted proteins from culture medium, soluble proteins such as s100A8 and s100A9, which have been shown to be associated with cancer cell invasion, were only detected in highly metastatic 5-8F cells, but not lowly-metastatic 6-10B cells." (PMID 33020562, 2020). "With S100A8, they represent damage-associated molecular pattern molecules (DAMPs), producing a complex that promotes cancer development and invasion, a promising target for the development of new strategies of treatment." (PMID 32290283, 2020). "Previous studies have shown that members of the S100 protein family are associated with various cancer entities; both S100A8 and S100A9 can promote proliferation, survival, and metastasis." (PMID 32503348, 2020). "On the other hand, putative M-MDSCs showed greater abundance of transcripts encoding both the IL4R, consistent with previous data, and S100A8, serum concentrations of which have been associated with poor cancer survival." (PMID 30837603, 2019). "Conditioned media from Panc-1, Suit-2 and BxPc3 cancer cell lines caused increased expression of S100A8 and S100A9 proteins in primary human monocytes." (PMID 30558665, 2018). "S100A8/S100A9 proteins regulate the behaviour of cancer cells by inducing pre-metastatic cascades associated with cancer spread." (PMID 30558665, 2018). "The heterodimeric S100A8/A9 is a predominant granule protein found in neutrophils and macrophages, possesses a key role in chronic inflammation, and has been implicated in cancer metastasis." (PMID 28955868, 2016).
cancer (continued). "CXCL1/2 promote recruitment of G-MDSCs which secrete S100A8/9, which results in amplifying the CXCL1/2-S100A8/9 loop and causing increased cancer cell survival, metastasis, and chemoresistance." (PMID 26078490, 2015). "We now report that downregulation of S100A8/A9 correlates strongly with a loss of cell cycle control and increased growth of carcinoma cells." (PMID 23874958, 2013). "Further investigation into the heterogeneity of myeloid cells revealed that clusters C9, 11, and 13 exhibited elevated expression levels of myeloid‐derived suppressor cell (MDSC)‐associated genes, such as S100A8 and S10019, which have previously been utilized for defining MDSCs in cancer models." (PMID 40289661, 2025). "The authors used Kaplan-Meier survival analysis and Cox regression analysis to determine whether S100A8 expression was associated with recurrence-free, progression-free or cancer-specific survival." (PMID 39895787, 2025). "S100A8/A9 often exist in the form of hetero-O dimer formation associated with cancer." (PMID 39897030, 2025). "This may be a limitation of the methods applied given that S100A8 has both known extracellular and intranuclear functions associated with cancer." (PMID 37450087, 2023). "Whether the expression of S100A8/S100A9 is a result of chronic inflammation related to cancer or plays a causative role in response to ICB therapy and patient prognosis requires further investigation." (PMID 37835599, 2023). "Only S100A8 protein expression in cancer cells was associated with significantly worse prognosis." (PMID 37450087, 2023). "Most recently, S100A8 has emerged as an immunogenic protein linked to cancer." (PMID 37174723, 2023). "Interestingly, the S100A8/A9 complex is linked to pro-inflammatory activities in numerous cancers and high expression of these proteins is often correlated to increased cancer growth and metastases." (PMID 35655772, 2022). "First, S100A8/A9 target sites are preferentially associated with annotated cancer genes." (PMID 33523865, 2021). "S100A8 has emerged as an inflammatory factor and is associated with cancer." (PMID 30456203, 2018). "In human primary tumors originating from tissues that normally express little or no S100A8 and S100A9 protein, such as skin, breast, thyroid, liver, gastric mucosa, prostate, ovary, bladder, and lung, S100A8/A9 levels are often elevated in association with tumorigenesis and cancer progression." (PMID 26883112, 2016). "To show that loss of S100A8/A9 expression contributes to HNSCC, we determined whether S100A8/A9 caused gain or loss of specific predicted functions using the S100A8/A9-negative carcinoma cell line, KB." (PMID 26883112, 2016). "To determine whether the dysregulation of S100A8/A9 in HNSCC is a cause or an effect of the cancer phenotype, we sought to determine a role in cell cycle regulation." (PMID 23874958, 2013). "Although S100A8/A9 gene expression in mucosal tissues of cancer-free individuals may be even greater, decreased S100A8/A9 expression levels are clearly associated with carcinogenesis." (PMID 23874958, 2013). "S100A8/A9 (calprotectin) is a calcium-binding heterodimeric protein complex implicated in cell cycle regulation, but the specific mechanism and role in cell cycle control and carcinoma growth are not well understood." (PMID 23874958, 2013). "As an example, calgranulins, S100A8/A9 (calgranulins A and B, respectively), have been detected in various human cancers; hence they have been suggested to play a key role in inflammation-associated cancer." (PMID 22509329, 2012). "Its expression and potential cytokine-like function in inflammation and in cancer suggests that S100A8/A9 may play a key role in inflammation-associated cancer." (PMID 20497537, 2010).
cancer (continued). "Altogether, their expression patterns, potential cytokine-like functions, up-regulation and regulation via signalling pathways, including tumor-promoting RAGE receptor, suggest that S100A8/A9 may play a key role in inflammation-associated cancers." (PMID 19440546, 2009). "Consequently, we may have overlooked potential associations between S100P/S100A8 and other cancers, particularly those with smaller sample sizes." (PMID 40224483, 2025). "In addition, S100A8 activation weakened Sec C activity, while S100A8 deficiency enhanced the Sec C lethal effect, which might play a profound role in cancer treatments." (PMID 38607060, 2024). "Importantly, overhaul exposure was associated with an up/down-regulation of 86 genes with a fold change of 1.5 or greater (p<0.5) including the immunomodulatory-linked genes S100a8 and Tnfsf9 (downregulation) and the cancer-linked genes, Capn11 and Rorc (upregulation)." (PMID 30130361, 2018). "S100A8/A9 heterodimer, an exosomal protein, contributes to metastasis, angiogenesis, and immunosuppression in various cancers." (PMID 39897030, 2025). "Studies have demonstrated that S100A8/A9 can stimulate the proliferation, migration and invasion of most cancer types." (PMID 39895787, 2025). "Calprotectin, a heterodimer of the S100A8 and S100A9 proteins, has been implicated in cancer-related inflammation and metastasis." (PMID 40869349, 2025). "Future work will focus on how cancer cells are influenced by S100a8/a9 regulated lipids and the role of S100a8/a9 in cancer cell metabolism via the mitochondria." (PMID 39796176, 2025). "First, we discuss S100A8/A9, which has emerged as a critical factor in various cancers, including GC." (PMID 40924339, 2025). "The survival analysis results indicated lower overall and cancer-free survival in the high S100A8 expression group than the low S100A8 expression group." (PMID 39895787, 2025). "Known for its regulatory roles in the immune system and as a marker of neutrophils, S100A8/A9 has demonstrated opposing effects across different cancer types." (PMID 40670349, 2025). "The survival analysis results implied that the high S100A8 expression group had a lower overall survival and cancer-specific survival than the low S100A8 expression group." (PMID 39895787, 2025). "This approach yielded insights into S100A8/A9-regulated gene expression profiles relevant to cancer progression." (PMID 40924339, 2025). "These cells expressed pro-inflammatory genes, such as Cd74, S100a8, and S100a9, which have been shown to contribute to the progression of various cancer types." (PMID 39425000, 2025). "The gene expression level of S100A8 in Pan cancer cell lines was analyzed through the Cancer Cell Line Encyclopedia (CCLE) database, and the HT-1376 cell line was selected for subsequent experiments." (PMID 39895787, 2025). "The rationale for this is that non-cancer cells, particularly myeloid cells, are the dominant sources of S100A8/A9 in developed tumors in mouse models of BC (Ref." (PMID 38378783, 2024). "Due to this complexity, the role of S100A8 in tumors needs to be investigated and evaluated carefully, taking into account the broader context of cancer biology." (PMID 38361783, 2024). "Mainly located in cytoplasm and nucleus, S100A8 can trigger multiple signal transduction pathways to mediate microtubule constitution and pathogen defense, as well as intricate cancer growth, metastasis, drug resistance, and prognosis." (PMID 39659236, 2024). "Low doses of S100A8 and A9 have been shown to promote cancer cell growth in a manner dependent on RAGE and the ERK/p38MAPK pathways, with no activation observed in the JNK pathway." (PMID 38250151, 2024). "In serum samples from 80 patients with surgically treated tumors, researchers found that patients with high serum S100A8/A9 concentrations experienced a significantly shorter period before cancer recurrence." (PMID 38404689, 2024).
cancer (continued). "Our research proves that Sec C is a promising prodrug for cancer treatment, and S100A8 can be a prospective target as well as biomarker for cancer screening and diagnosis." (PMID 38607060, 2024). "Decreased proportions of CD14.Mn.S100A8.9hi cell subsets were observed in NACT-treated cancer patients compared to healthy controls (log2FC=0,824, FDR=0,1)." (PMID 39315092, 2024). "MDSC-derived S100A8/A9 significantly elevates the release of human matrix metalloproteinases from cancer cells to catabolize the ECM, increasing the invasiveness of proliferative BC tumors and causing widespread recurrence and metastasis." (PMID 38404689, 2024). "Calprotectin, a heterodimer formed from the combination of S100A8 and S100A9 proteins, is commonly upregulated in many tumors and likely plays a critical (essential) role in inflammation-associated cancers." (PMID 39201484, 2024). "Among these, STAT3 is regularly supported in the literature as essential for S100A8/A9 expression in both cancer and immune cells, and C/EBPβ has also been shown to control S100A8/A9 expression in a cancer cell model." (PMID 38378783, 2024). "In our previous study, we reported that pulmonary vessels of autopsy samples contained S100A8/A9, as expected in cancer patients." (PMID 37620307, 2023). "Overexpression of S100A8 in cancer cells has been studied in several different populations of BC patients and has consistently been found to be associated with poor clinicopathological features and reduced survival." (PMID 37450087, 2023). "The S100A8 and S100A9 genes are located on chromosome 1q21, and the deletion or mutation of these chromosomes is associated with the occurrence of cancer." (PMID 36768433, 2023). "S100A8 was found to be amplified exclusively within cancer cells, where it was found in a pattern consistent with extrachromosomal amplification." (PMID 37450087, 2023). "Currently, some tactics aimed at S100A8/A9 and its receptors in cancer treatments have been studied, such as chemical drugs, specific antibodies, antagonists, and peptides." (PMID 37701037, 2023). "This study discovered novel PC-derived cachexigenic factors S100A8, S100A9, and S100A8/A9 heterodimer that potentially mediate muscle wasting, the hallmark of cancer cachexia, and thus have important prognostic and therapeutic implications." (PMID 37280516, 2023). "In the clinical setting, S100A8/A9 and its receptors can be used complementarily as efficient biomarkers for cancer diagnosis and treatment." (PMID 37701037, 2023). "Proinflammatory cytokines S100A8/S100A9/S100A11 are calcium‐binding proteins that are upregulated in human cancer." (PMID 36967480, 2023). "A low concentration of S100A8/A9 promotes cancer cell proliferation mainly by inducing phosphorylation of p38 and p44/42 MAPK." (PMID 38093319, 2023). "The pro-inflammatory molecules S100A8/A9 and high mobility group box protein 1 (HMGB1) and their receptor RAGE are strongly associated with the initiation and progression of most cancers." (PMID 36831371, 2023). "In the cancer cell lines, statistically significant correlations were found between S100P and S100A8 (R = 0.91), and S100A11 (R = 0.73)." (PMID 37627239, 2023). "Accordingly, we focused on the roles and mechanisms of S100A8/A9 in cancers to summarize the research advances, expecting to provide valid theoretical support for this study and future perspectives." (PMID 37701037, 2023). "Consistently, the expression of S100a8 gene in the lungs of 67NR, 4T07, and 4T1 cancers were 15.3-fold, 31.1-fold, and 39.5-fold, respectively, higher than that in the healthy lungs." (PMID 37553342, 2023). "Due to the characteristics of participating in the recurrence and metastasis of a variety of cancers, Fn-1, S100A8, S100A9, and MMP9 were regarded as the main components of the formation of the pre-metastatic microenvironment." (PMID 37330523, 2023).